SQSTM1 (sequestosome 1)
Diseases named in the same sentence as SQSTM1 in open-access papers (continued):
Sharing a sentence is not in itself a finding about the gene and the disease.
tumor (continued). "Autophagy can not only directly down-regulate PD-L1 through the p62/SQSTM1-NF-κB pathway, but also down-regulate PD-L1 by reducing the expression of histone deacetylase (HDAC), participating in the activation of tumor immunity." (PMID 40438098, 2025). "Likely due to the greater sequencing read depth, patient 1,010,020 had a substantially greater number of such genes—a total of 187; these likewise included several tumor suppressor genes, such as ANGPTL4, ARHGEF10, MARVELD1, and SQSTM1." (PMID 41428220, 2025). "Immunohistochemistry reveals tumor cell positivity for CD30, CD68, CD163, ALK1, ALK (D5F3), and EMA; Genetic testing shows ALK gene rearrangement in tumor cells but with different ALK fusion partners, mainly SQSTM1 (52%) and VCL (30%)." (PMID 38706599, 2024). "In macrophages from tumor samples, two NPA genes, GLUL and SQSTM1, were found to be up-regulated, while SLC25A6 exhibited down-regulation." (PMID 38149248, 2023). "Although GLUL-SQSMT1- RTM was specifically present in PDAC tumor tissues, it was noteworthy that the majority of RTM in the TME are characterized by the expression of GLUL and SQSTM1." (PMID 38149248, 2023). "SQSTM1-mediated stable expression of TWIST1 promotes EMT in vitro and promotes tumor growth and metastasis in mice." (PMID 37403096, 2023). "Here, JQ1 significantly inhibited tumor growth and induced autophagic flux, as indicated by elevated levels of LC3II and p-ULK1, as well as p62/SQSTM1 degradation." (PMID 37628849, 2023). "In GB7225 specimen with high level of autophagy (higher expression of LC3B, STX17 and lower expression of SQSTM1), HMGB1 in the nuclei and cytoplasm of tumor cells was significantly diminished." (PMID 35193644, 2022). "Of the 21 MRGs, ATG9A, PGAM5, SQSTM1, and GABARAPL1 were differentially expressed at the transcriptomic level between tumor and normal tissues." (PMID 36292980, 2022). "The result showed that SQSTM1-positive cells were reduced and LC3B-positive cells were elevated in GNIP1-expressing tumours, revealing that GNIP1 is involved in autophagy." (PMID 36042481, 2022). "Three genes (SQSTM1, G6PD, and CDK1) were classified into risky group with HR >1 related to poorer prognosis and presented higher expression levels in tumor tissues than in normal tissues." (PMID 35711939, 2022). "Three genes (SQSTM1, G6PD, and CDK1) were upregulated in the tumor tissues compared to the HCC normal tissues in the TCGA-LIHC dataset." (PMID 35711939, 2022). "By immunoblot analysis, our data showed a decreased expression level of LC3-II with an increased level of SQSTM1, cleaved PARP, and caspase 9/3 in tumor of T-DM1 combined with LY294002 group versus T-DM1-treated group." (PMID 33731670, 2021). "Using this approach, we observed significantly more positive SQSTM1/LC3B interactive signals, most of which located in the cytosol, in cancer cells at the invasive front than in cancer cells inside the tumor body." (PMID 34483138, 2021). "Our results show that the expression levels of SQSTM1 and EGFR proteins are higher in tumor tissues than in the corresponding tumor-adjacent (CTAN) tissues of OSCC patients." (PMID 34830108, 2021). "Both expression levels of EGFR-M and EGFR-C were higher in tumor tissues than that in CTAN tissues (all p < 0.001) but only EGFR-C expression was positively correlated with SQSTM1 expression." (PMID 34830108, 2021). "As an initiating event, we then looked for a partner of SQSTM1, the K63 deubiquitinase CYLD, which is a tumor suppressor that constitutively regulates the NF-κB pathway by removing K63-linked ubiquitin chains from TRAF6." (PMID 34065348, 2021). "Analysis of clinical samples validated the overexpression of the 4 genes (SQSTM1, BIRC5, NRG3, and CXCR4) in tumor tissues relative to paired normal tissues, consistent with bioinformatic findings." (PMID 34484469, 2021).
tumor (continued). "P62/SQSTM1 staining revealed an increase in diffuse cytoplasmic P62/SQSTM1 staining, as well as the presence of P62/SQSTM1 bodies in the cytoplasm in both HT29- and Hep3B-CdtB-derived tumor cells." (PMID 33662035, 2021). "Among SQSTM1 signaling partners, we provide the first evidence that the activity of CYLD K63 deubiquitinase, a tumor suppressor, was repressed by Cd, likely via ubiquitination, processing, and aggregation." (PMID 34065348, 2021). "Genes ASPH, HSPB1, SQSTM1, ANXA2, and GSN (Cluster A) and PURA and MX1 (Cluster B) were downregulated for both datasets in PCa tissue vs. normal gland or normal adjacent to tumor tissue." (PMID 32640729, 2020). "Immunohistochemical staining of primary tumor tissues of 137 patients with gastric cancer showed that LC3 and p62/SQSTM1 protein levels were positively correlated with PD-L1 (LC3, p < 0.001; p62/SQSTM1, p < 0.05)." (PMID 30925913, 2019). "Inactivation of both P62/SQSTM1 and LSD1 in these cells strongly reduced tumor growth in rodent models." (PMID 31861179, 2019). "NTZ significantly inhibited tumor growth, which resulted in decreased tumor weight and volume in the NTZ group In addition, elevated levels of ING1, LC3 and SQSTM1 were observed in the NTZ group compared with the control group." (PMID 30302016, 2018). "BIRC5, FOXO1 and SQSTM1 protein expression level were detected by immunohistochemistry (IHC) in 302 HCC tissues and in 41 non-tumor tissues." (PMID 29707114, 2018). "Moreover, given that GABARAPL1 G116A, which predominately cannot conjugate to autophagosomes and interacts less with SQSTM1, still presented a tumor suppressor role, we might think that GABARAPL1 function in selective autophagy is not essential for its tumor suppressive function." (PMID 28915569, 2017). "In conclusion, this pan-cancer analysis identifies p62/SQSTM1 as a conserved, clinically relevant regulator linking oncogenic metabolism (oxidative phosphorylation, ROS, mTORC1, UPR/MYC, and DNA-repair programs) to the tumor immune microenvironment." (PMID 41291343, 2025). "At higher concentrations, autophagy and lysosome biogenesis genes, such as SQSTM1/p62, LAMP2, and PINK1, were robustly upregulated along with tumor suppressors, such as PTEN, and pro-apoptotic factors, including BAD and BIK, which reinforce autophagic flux and promote cellular homeostasis." (PMID 40671124, 2025). "Further analysis revealed a positive correlation between PAI-1 expression and autophagy markers p62 (SQSTM1) and Cathepsin D (CTSD) in GBM tissues, suggesting that PAI-1 may be modulating GBM tumor biology through the process of autophagy." (PMID 40684232, 2025). "In addition, considering the complexity of the tumor microenvironment (TME), we also studied the effects of SQSTM1/p62 on the migration of HCC in the LPS-induced THP-1 macrophage inflammatory model." (PMID 37174639, 2023). "Additionally, a significant increase in SQSTM1/p62 levels were observed when comparing the CQ treated WT and SAADKO tumor groups." (PMID 36248994, 2022). "While SREBP1 and E-FABP mRNAs were widely expressed with similar distribution patterns, p62/SQSTM1 mRNA showed modest expression in the tumor mass without resveratrol treatment." (PMID 36500345, 2022). "Differential gene expression analysis by Seurat34,35 identified 160 genes uniquely upregulated in tumor cells compared with TAF and normal kidney, including genes previously reported (e.g., GPNMB8, SQSTM1/p6236, MMP237, PTGDS38) and genes involved in tumor metastasis (e.g. MMP11, MDK, DCN, PDPN)." (PMID 36028490, 2022). "However, in GB1388 specimen with lower levels of autophagy (lower expression of LC3B, STX17 and higher expression of SQSTM1), HMGB1 accumulated in the nuclei and cytoplasm of tumor cells." (PMID 35193644, 2022).
tumor (continued). "To investigate the correlation of autophagy at the invasive front with patient prognosis, we studied the interaction of SQSTM1 and LC3B in 148 NSCLC specimens, including 39 LUSC and 99 LUAD specimens, and in 10 tumor-adjacent lung tissues using bright-field PLA." (PMID 34483138, 2021). "No PLA signal of SQSTM1/LC3B interaction was detected in epithelial cells in tumor-adjacent lung tissues, indicating a relatively low autophagic flux." (PMID 34483138, 2021). "Downstream, K63-Ub/SQSTM1 accumulation results in the sequestration of damaged mitochondria, the CYLD K63 DUB, and the activation of the K63-Ub TRAF6-NF-κB pathway, providing metabolic, survival, inflammatory, and proliferative advantages to tumor cells." (PMID 34065348, 2021). "Cancer cells at the invasive strand and cancer cells inside the tumor body, which exhibited different cytoplasmic/dot-like SQSTM1 staining, showed similar HIF1α staining intensity (data not shown)." (PMID 34483138, 2021). "Additionally, the intracellular iron exporter FPN is now identified as a substrate for autophagic elimination, and its degradation by SQSTM1/p62 promotes erastin/RSL3-mediated ferroptosis in vitro and in xenograft tumor mouse models." (PMID 34831207, 2021). "Third, SQSTM1 was positively correlated with MAP1LC3B in the tumor tissues of BMSCC, but not in adjacent normal tissues." (PMID 30477228, 2018). "The SQSTM1 protein level was also found to be positively correlated with MAP1LC3B in the tumor tissues of BMSCC but not in adjacent normal tissues." (PMID 30477228, 2018). "Furthermore, HULC overexpression in vivo induced tumor formation, and reduced ATG7, LC3 expression, while inducing SQSTM1 expression; however, we found that HULC overexpression did not influence ATG5, ATG12, Beclin-1, VPS34, P150 or UVRAG expression." (PMID 29022892, 2017). "To further assess whether tumor suppression was related to autophagy induced by EMC6, we detected LC3B and SQSTM1 by immunofluorescence in the null, mock and EMC6-overexpressing groups of mice." (PMID 26775697, 2016). "An analysis of JIMT-1 tumor tissue indicated that the liposomal HCQ and gefitinib combination augmented the inhibition of autophagy in vivo compared to the free HCQ and gefitinib combination as demonstrated by increased LC3-II and p62/SQSTM1 (p62) protein levels." (PMID 39861690, 2024). "Importantly, clinical ovary cancer sample analysis consistently validates the relevance of PCBP1 expression to both p62/SQSTM1 and caspase-8 to overall survival, and indicates PCBP1 may be a master player to repress tumor initiation." (PMID 32922440, 2020). "Conversely, downregulation of ATG7 reduced m-THPC-PDT-induced autophagy in tumor tissues, as revealed by the m-THPC-PDT-induced increase in MAP1LC3B-II protein expression and a decrease in SQSTM1/p62 expression that could be counteracted by ATG7 downregulation." (PMID 33130826, 2020). "Finally, treatment with rapamycin induced LC3-II, ATG7, ATG12 and Bcl2 expression and reduced the levels of SQSTM1/p62 and Bax, indicating that autophagy can protect tumour cells from the negative effects of HMGA2 knockdown." (PMID 31053152, 2019). "Moreover, in vivo xenograft models, the mice given stable overexpressed miR-590-3p cells and treated with EMAP-II and TMZ had the smallest tumor sizes, besides, miR-590-3p + EMAP-II + TMZ up-regulated the expression level of miR-590-3p, LC3-II and Beclin-1 as well as down-regulated p62/SQSTM1." (PMID 28348518, 2017). "Moreover, whether downregulating the expression of p62/SQSTM1 can effectively sensitize PTX-resistant tumor is also not known." (PMID 35574313, 2022). "To further investigate the role of p62/SQSTM1 in the sensitization to TRAIL observed in GBM cells after PIM disabling, we performed co-immunoprecipitation assays to test whether p62/SQSTM1 interacts with caspase-8 upon TRAIL treatment as reported in other tumor cells." (PMID 30718520, 2019).
cancer (157 papers, 2013 to 2026). A tumor composed of atypical neoplastic, often pleomorphic cells that invade other tissues. "Sequestosome1 (SQSTM1 or p62), hereafter p62, an autophagy receptor, has been associated with aging and age‐related diseases, including neurodegeneration, infections, cancer, and oxidative stress‐related conditions." (PMID 40344296, 2025). "The identification of specific molecular targets like SQSTM1/P62 and the enrichment of cancer-related pathways elucidate the biology underlying this process." (PMID 41472277, 2025). "Another PRG associated with STAD prognosis is SQSTM1, whose alteration is implicated in autophagy and has been linked to gastric tumorigenesis and cancer progression." (PMID 41004487, 2025). "Among these cancer types, it was determined that the increased expression of the SQSTM1/P62 gene was associated with THYM (HR = 2.27, p = 0.0442) and its poor prognosis." (PMID 41472277, 2025). "In another study, inhibition of autophagy activated the NF-κB/Snail pathway and induced EMT under the control of SQSTM1/p62 in RAS mutated cancer cells." (PMID 38398197, 2024). "Conversely, p62/SQSTM1 levels, which accumulate when autophagy is impaired, have been linked to poor prognosis in various cancers." (PMID 39199310, 2024). "Mutation analysis of TCGA dataset in TIMER, cBioportal, and DriverDBv3 portals shows that the Sqstm1 gene undergoes near 8% of point mutation, followed by amplification and deep deletion, in various cancers." (PMID 35814476, 2022). "Although the mechanism is not clear, we demonstrated that itaconate causes cell death and DAMP (HMGB1 and SQSTM1) release, which is consistent with recent studies on the cytotoxicity of itaconate on cancer cells." (PMID 35769880, 2022). "In mouse embryonic fibroblasts and human cancer cell lines, autophagy deficiency leads to the accumulation of the SQSTM1/p62 which by binding TWIST1 and SNAI1, leads to their stabilization and thereby increased migration and loss of epithelial markers." (PMID 34944948, 2021). "Increased protein levels of MAP1LC3B and SQSTM1 are considered to be causes of autophagy inhibition or activation in various types of cancers." (PMID 34829743, 2021). "Previously, we reported that the administration of a p62/SQSTM1-encoding plasmid demonstrates high safety and signs of clinical benefits for human cancer patients." (PMID 31754084, 2019). "p62, encoded by SQSTM1, is the most well-known autophagy adaptor, and it plays a crucial role in both normal physiology and cancer." (PMID 31708690, 2019). "High levels of cytoplasmic SQSTM1 have also been found to be associated with poor survival in several cancer types." (PMID 30477228, 2018). "Both proteins are essential for the autophagy machinery, and high expression levels of MAP1LC3B and SQSTM1 are significantly associated with an unfavorable clinicopathological outcome in several cancer types, including OSCC." (PMID 30477228, 2018). "In a recent report 3, Hu and his colleagues have verified that TRIB3, a stress‐induced protein, links metabolic risk factors to cancer development and progression via interacting with SQSTM1, a selective autophagy receptor." (PMID 27038142, 2016). "p62/SQSTM1 excess can cause low grade dysplasia in the oral epithelium to develop into carcinoma via the resistance to various oxidative stresses." (PMID 24086340, 2013). "In addition, SQSTM1/p62 has been used as a marker of autophagy and aberrant levels of SQSTM1/p62 have been associated with PC and cancer progression." (PMID 35318456, 2022). "Then, risk scores were calculated for every cancer sample calculated by using the following formula: Riskraw = DAD1*2.316+CYCS*1.426+CSNK2A2*1.576+VPS25*0.728+VDAC1*0.976+TMLHE*0.381+CYTH3*0.024+PRKCA*0.260-TP73*0.567+FZD6*0.047+SQSTM1*0.094-MAP2K7*3.070." (PMID 35185897, 2022).
cancer (continued). "Besides, ROS can modulate autophagy by affecting the activity of various transcription factors such as NF-κB, resulting in the expression of autophagy-associated genes (BECN1/ATG6 or SQSTM1/p62) in cancer cells." (PMID 31583051, 2019). "Interestingly, SNAI1 proteins were physically associated and colocalized with LC3 and SQSTM1 in cancer cells." (PMID 30736337, 2019). "Autophagy is involved in cancer metastasis, and SQSTM1 is associated with lymph node invasion." (PMID 30477228, 2018). "In Nrf2 deficient cancer cells, the increased SQSTM1 protein and mRNA was reversed." (PMID 29789637, 2018). "TCGA provisional data analysis showed a significant positive association between SQSTM1 and ER stress-induced TFs expression in 15 cancer types, supporting the notion that SQSTM1 might be an attractive therapeutic target in some ER-stressed cancers, if not all." (PMID 40396020, 2022). "Therefore, targeting autophagy and the autophagy-associated SQSTM1 gene expression could be exploited for developing more effective cancer treatments." (PMID 32807131, 2020). "Targeting SQSTM1 (p62) in combination with NRF2 inhibitors has emerged as a promising therapeutic strategy in the treatment of cancers, especially in those malignancies with high expression levels of both proteins." (PMID 39941813, 2025). "Further, elevated expression of key autophagy proteins beclin-1, ATG-7, LC-3-I/II, and SQSTM1/p62 reveal that inhibition of autophagy plays a crucial role in regulating DDR capabilities of cancer cells." (PMID 40041432, 2025). "Dysregulation of mitophagy-related proteins, such as FUNDC1, Parkin, BNIP3, BNIP3L/NIX, and p62/SQSTM1, has been shown to be correlated with cancer." (PMID 39524226, 2024). "The role of STAT3 inhibitors in treating SQSTM1-ALK fusion-positive cancers, as well as the combination of ALK and STAT3 inhibitors, warrants further investigation." (PMID 39555099, 2024). "The importance of SQSTM1 in catabolic processes (i.e. autophagy and proteostasis) is pivotal for the understanding of disorders such as neurodegenerative disorders, cancers, and metabolic syndromes." (PMID 39098523, 2024). "SQSTM1 is a ubiquitin-binding autophagy receptor that exhibits oncogenic activity in various cancers." (PMID 38265972, 2024). "Conversely, autophagic substrate SQSTM1, which is degraded efficiently following the incorporation into autophagosome, was remarkably downregulated in cancer cells." (PMID 39334351, 2024). "Dysregulation of mitophagy, involving proteins such as Parkin, PINK1, BNIP3, BNIP3L/NIX and p62/SQSTM1, further exacerbates tumour growth and metastasis by fueling cancer cell energy demands and enhancing cell survival through anti‐apoptotic pathways." (PMID 38534098, 2024). "In recent years, several studies have confirmed that SQSTM1/p62 is overexpressed in various cancers." (PMID 37174639, 2023). "The interaction of TRIB3 and the autophagic receptor P62 (Sequestosome 1) interferes with the degradation of autophagy and the ubiquitin–proteasome system to control the initiation and progression of cancer." (PMID 37042179, 2023). "Staurosporine alleviates cisplatin chemoresistance in human cancer (colon) cell models by suppressing the induction of SQSTM1/p62." (PMID 36991484, 2023). "In this study, HA1 inhibited autophagy by triggering the accumulation of LC-3-II and SQSTM1, thereby inhibiting cancer survival because cancer cells tend to be more dependent on autophagy compared with normal cells." (PMID 36831614, 2023).